LINC01359 (long independently transcribed non-coding RNA 1359)
Gene: Long non-coding RNA gene on chromosome 1 (64,972,225 to 65,002,489, reverse strand). Ensembl gene ENSG00000226891.
Diseases named in the same sentence as LINC01359 in open-access papers:
LINC01359 is named in the same sentence as 4 diseases in open-access papers, as found by Europe PMC text mining. Sharing a sentence is not in itself a finding about the gene and the disease. The quoted sentences say what the papers report.
asthenozoospermia (2 papers, 2022 to 2023). "LINC01359 is also deregulated in asthenozoospermia and oligozoospermia, whereas the host gene of SLC16A1-AS1, SLC16A1, is connected to spermatogenic defects." (PMID 37834450, 2023). "LINC01091 and LINC01359 were also found to be deregulated in the three main subtypes of male infertility, namely asthenozoospermia, teratozoospermia, and oligozoospermia." (PMID 36290414, 2022).
cancer (1 paper, 2019). A tumor composed of atypical neoplastic, often pleomorphic cells that invade other tissues. "Using Cytoscape, we were able to segregate the subnetwork of 76 genes potentially governed jointly by TINCR (65 genes) and LINC01359 (55 genes), which resulted in submodules of genes with core histone protein domains (green nodes) and involved in pathways in cancer (blue nodes)." (PMID 30959550, 2019).
LINC01359 also shares sentences with these, for which no sentence is quoted: male infertility (1 paper); teratozoospermia (1).